INS (insulin)
Diseases named in the same sentence as INS in open-access papers (continued):
Sharing a sentence is not in itself a finding about the gene and the disease.
cancer (continued). "Thus, the similarity of T2D profile at baseline across three race/ethnic groups were limited to being insulin naïve, under reasonable glycemic control, and without a history of cancer, CVD, and CLD." (PMID 30993905, 2019). "Interestingly, while we found no such data in cancer patients, we found a trial in insulin-resistant patients that have compared the source of ω3." (PMID 31315273, 2019). "In addition, high levels of insulin and insulin-like growth factors (IGF-I) found among pre- and postmenopausal obese women could stimulate the development and growth of cancer cells." (PMID 31360892, 2019). "Indeed, a related phenomenon is seen in patients with cancer who are treated with phosphatidyl-inositol 3-kinase (PI3 K) inhibitors, who often secrete extra insulin to compensate for the insulin resistance induced by the drugs, thus reducing their anti-cancer efficacy." (PMID 31288625, 2019). "Further examination of the critical insulin and glucose signaling pathways is warranted to better understand how ACVR2B/Fc treatment may mitigate some of the glucose derangements that occur with cancer-induced and chemotherapy-induced cachexia." (PMID 31438622, 2019). "The top eight representative pathways were “pathways in cancer”, “neuroactive ligand receptor interaction”, “MAPK signaling pathway”, “regulation of actin cytoskeleton”, “focal adhesion”, “calcium signaling pathway”, “wnt signaling pathway” and “insulin signaling pathway”." (PMID 31422382, 2019). "Thus, in the absence of androgens, insulin modulates the molecular profile of cancer cells consistent with a more invasive phenotype." (PMID 31379747, 2019). "SIRT2 also directs other physiological processes, including gluconeogenesis, insulin sensitivity, and fatty acid oxidation, and is critical for insulin-dependent AKT activation, suggesting that the inhibition of SIRT2 may have an impact on cancer growth." (PMID 30405152, 2018). "Interestingly, insulin signaling, including the FBP-1 gene, was the most highly enriched in down-regulated DEGs, but we know that down-regulation of FBP1 promotes tumor metastasis and indicates poor prognosis in other cancers." (PMID 30205506, 2018). "Hence, we speculate that PDGFA is probably also induced by either bFGF or insulin to lead to the autocrine mechanism of PDGF–PDGFR activation because PDGFR plays a crucial role in triggering and maintaining cancer stemness." (PMID 30068339, 2018). "Importantly, cancer tissue analysis showed a very small amount of insulin and IGF1 receptors compared to non-operated or dyplastic tissue or both in all groups of animals, with the exception of WT females." (PMID 29662006, 2018). "Unlike them, we hypothesize that cancer tissue may produce omentin to increase insulin-induced glucose intake in tumor, as omentin increases tissue sensitivity to insulin." (PMID 30186533, 2018). "It has been proposed that metformin exerts its anti-cancer properties through direct effects on cancer cells, particularly through inhibition of the AMPK/mTOR pathway, and indirect effects by decreasing glucose, insulin, insulin-like growth factor 1 (IGF-1) levels, and other inflammatory factors." (PMID 29113364, 2017). "Inhibition of insulin mediated genotoxicity may be relevant for cancer protection of patients with elevated insulin levels and the mTOR pathway has not been investigated for this purpose before." (PMID 29231877, 2017). "Importantly, glycans was also shown to regulate the insulin/IGF signaling pathway in a cancer context, which highlights its importance in the regulatory circuits that integrate metabolic alterations, cancer drug resistance, and cancer cell behaviour." (PMID 28880250, 2017). "Here, we show that a specific miRNA, miR-4443, responds to leptin and insulin treatment in CRC-derived cells and that its impaired regulation may contribute to deregulation of downstream signaling, increased cancer metastasis and worse prognosis in a state of leptin resistance." (PMID 27842582, 2016).
cancer (continued). "Insulin use and smoking significantly predicted cancer and non-cancer death." (PMID 27906989, 2016). "There is no increase in death by cancer with insulin therapy vs. placebo/diet." (PMID 27391319, 2016). "Moreover, bariatric and metabolic surgery are interventions with additional proven insulin-sensitizing effects that reduce the detrimental signaling effects of the insulin/IGF1 axis, thereby exerting a positive impact on the incidence of cancer." (PMID 27612200, 2016). "The mechanisms by which metformin affects cancers are also unknown, although a large number of publications have shown that metformin could exert its antitumor effect by targeting AMPK/mTOR, anti-inflammatory, cell cycle/apoptosis, insulin/IGF-1R, and angiogenesis pathways in cancers." (PMID 27517917, 2016). "Although not statistically significant, insulin tends to suppress cancer cell apoptosis." (PMID 26939025, 2016). "Although changes were not seen in the current study it is worth investigating further whether or not CLMIT and LVHIIT exercise programs have an impact on insulin levels in cancer survivors." (PMID 27781180, 2016). "On one side, as insulin is an anabolic factor that normally blocks protein breakdown and promotes protein synthesis;159, 160 insulin resistance (and similarly IGF-1-resistance) might promote muscle wasting, hence, amino acid mobilization into the circulation, potentially fueling cancer." (PMID 26900952, 2016). "Insulin use and smoking were significantly predictive for both cancer death and non-cancer death." (PMID 27906989, 2016). "The published animal studies on insulin analogues and cancer have not been reviewed so far." (PMID 26242987, 2015). "Firstly, problems related to the identification of the denominator: not possible to identify patients who had started insulin therapy (3 areas), patients referred for the first time to the secondary care level (2 areas), and patients referred to secondary care for suspected cancer (1 area)." (PMID 26268694, 2015). "However, several experts in the field of insulin/IGF signaling have suggested that these findings do not indicate that this system is a poor cancer treatment target." (PMID 26029167, 2015). "Adjusted hazard ratios (AHRs) of cancer in DM patients with and without insulin injection." (PMID 25978841, 2015). "Both in normal and cancer cells, GSK3β inactivation, through Ser9 phosphorylation, may occur by stimulation of the PI3K/Akt and the MAPK pathways in response to several mitogens, including insulin and paracrine/autocrine IGFs." (PMID 24550888, 2014). "However, the mechanisms of insulin in glucose metabolism in cancer cells have not been directly examined." (PMID 24895527, 2014). "Administration of silymarin to cancer patients may affect insulin sensitivity, which should not be ignored clinically." (PMID 24404172, 2014). "However, it is also important to take a “non-glucose/insulin resistant-centric view” with respect to the role of adipose tissue macrophages and to appreciate that they could also contribute significantly to the risk of other associated diseases including cardiovascular disease and cancer." (PMID 25309549, 2014). "Moreover, further adjustment of insulin dose did not affect this neutral effect of glargine insulin on incidence of cancers." (PMID 25329887, 2014). "Furthermore, receptors for insulin and IGF-1 are expressed in most cancer cells." (PMID 23431471, 2013). "However, chronic insulin signalling in the context of ADT might be complex and highly differentiated from those observed in other cancers." (PMID 23573093, 2013). "Moreover, insulin and IGF receptors are broadly expressed by normal tissue as well as cancer cells." (PMID 23476808, 2013).
cancer (continued). "Unfortunately, it is not safe to draw conclusions for insulin signaling and metabolism using cancerous cell lines as although cancer and normal cells use the same metabolic pathways, cancer cells are not so dependent on external signaling by insulin and other growth factors." (PMID 23363332, 2013). "However, concerns on cancer should not prevent physicians from prescribing insulin, even at high doses, when an adequate glycemic control cannot be reached otherwise: the benefit of metabolic control certainly exceeds the potential risks for malignancies." (PMID 24348585, 2013). "We observed 98 cancer events in the insulin use cohort and 170 in the non-insulin use cohort." (PMID 23308218, 2013). "Although the insulin users showed higher risks of overall and cancer mortality than the non-insulin users in this study, caution should be used in interpreting the results because individuals treated with insulin were more likely to be advanced diabetic patients." (PMID 23308218, 2013). "Crude incidence rate of cancer and mortality among insulin users vs. non-insulin users." (PMID 23308218, 2013). "In fact, in the only study in which the incidence of malignancies was reduced in insulin-treated patients, a nonsignificant trend toward an increased cancer mortality was observed, suggesting that insulin therapy could increase the lethality of cancer." (PMID 23209929, 2012). "Indeed the effects of metformin have not yet been demonstrated to be direct effects on cancer cells or an indirect consequence of systemic insulin normalisation." (PMID 22548055, 2012). "The outcome numbers were small, with 32 cancer cases in insulin users and 120 in non-users." (PMID 22719946, 2012). "This group determined that metformin was associated with lower overall mortality (3.5% versus 4.9% for the sulfonylurea cohort) and mortality as a result of cancer (an HR of 1 for metformin and no insulin use versus an HR of 1.3 (CI 1.1-1.6) for the sulfonylurea group)." (PMID 22203527, 2011). "Thus IR inhibition in cancer celllines (LCC6 and T47D) causes reduced Akt activation by insulin, with no involvement ofthe IGF-1R." (PMID 23908801, 2011). "While cell culture and mouse models have been integral to the characterization of the mechanism of action of metformin in the inhibition of cancer, they are artificial and rely on non-physiological doses of metformin in the presence of excess insulin and growth factors." (PMID 21470407, 2011). "HT-29 epithelial cancer cells were treated with 10 combinations of saturating or subsaturating concentrations of TNF, EGF and insulin (0, 0.2, 5, 100 ng/ml TNF and 0, 1, 100 ng/ml EGF or 0, 1, 5, 500 ng/ml insulin respectively), which collectively represent all the cues used in the study." (PMID 17559646, 2007). "Similar to how natural compounds like Rebeccamycin are thought to exert anti-cancer effects by modulating the PI3K/AKT signaling pathway, JadeAging may potentially achieve its anti-aging and antioxidant effects through the modulation of the insulin/IGF-1 and TOR pathways." (PMID 41601965, 2026). "Previous observations have linked JPH to reduced mTORC1 and Akt activation, although it should be noted that many of the mechanistic observations of JPH have been shown using cancer cell culture models, which may not be representative of normal muscle insulin signaling." (PMID 37367923, 2023). "Therefore, it is plausible that the insulin-attenuating action of metformin may present only in the absence of an aspirin-induced increase in plasma insulin concentration and that aspirin use could result in net harm for cancer outcomes." (PMID 36857596, 2023). "An increased expression in pancreatic islets might be related to an increase in fetal insulin secretion at that particular age group.In addition, adenoviral vectors and CAR have been widely utilized in cancer gene therapy, rapidly developing areas in pre-clinical and clinical cancer research." (PMID 37153286, 2023).
cancer (continued). "Because the classification of cancer stage based on data from the Finnish Cancer Registry was relatively crude, residual confounding by stage might be present if persons using only metformin on average had an earlier stage disease compared to those using other oral ADM and/or insulin." (PMID 36139140, 2022). "Interestingly, on the same hand, emerging reports suggest that the expressions of insulin and IGF receptor isoforms vary according to tissue types and ligand bioavailability and that there are therapeutic selective dependencies for distinct subtypes of PI3K pathway altered in cancer." (PMID 36017326, 2022). "Furthermore, a crosstalk between insulin-induced ERK and epidermal growth factor (EGF) favored tumorigenesis by triggering the expression of anti-tumor immunity inhibitor programmed death-ligand 1 (PD-L1) in a cancer common in individuals with insulin resistance, pancreatic ductal adenocarcinoma." (PMID 36017326, 2022). "Notably, the expression levels of normal pancreatic epithelial cell markers, SST and INS, were specifically higher compared to cancer cells, suggesting the normal functions of these cells, while malignant marker genes, SOX9 and KRT18, were remarkably upregulated in cancer cells." (PMID 35941362, 2022). "Cancer cells do not become insulin resistant, insulin resistance leads to the body producing more insulin to compensate, which, combined with an overexpression of insulin receptors on cancer cells, may lead to the promotion of cancer initiation and progression." (PMID 34822385, 2021). "In addition, insulin mediates insulin receptors, up-regulates MMP-2 expression, stimulates insulin receptor substrate-1 (IRS-1), and then activates the PI3K/AKT and MAPK signaling pathways to promote cancer cell proliferation and enhance cancer cell migration ability." (PMID 34485124, 2021). "In addition, due to the similar structure of insulin and IGF-1, IGF-1 can indirectly act on the heterozygous receptor to play its biological function, promote the corresponding signal transduction and cell proliferation, thus increasing the possibility of malignant tumor." (PMID 33468224, 2021). "Using the hyperinsulinemic-euglycemic clamp, the gold standard for measuring insulin sensitivity, whole-body insulin resistance has been established in pancreatic, lung, gastrointestinal system, and colorectal cancers; although none of those studies determined tissue-specific glucose uptake." (PMID 33801684, 2021). "However, not all cancers are responsive to insulin, and there might be types of cancer in which the reduced insulin concentration is insufficient to show anticancer effects." (PMID 33029097, 2020). "Besides, the serum concentrations of inflammatory cytokines, glucose, insulin and free IGF-1 are notably elevated in obese patients and provide a pro-tumorigenic environment that may explain the worse prognosis of obese patients with cancer." (PMID 33374289, 2020). "As TGF-β has many important effects on cancers, particularly in relation to differentiation status and stimulating epithelial to mesenchymal transition (EMT) this interaction may have potential implications for interactions between the insulin/IGF-system and these other regulatory pathways." (PMID 30809194, 2019). "Moreover the direct impact of insulin on cancer chemoresistance is absent." (PMID 26084465, 2015). "If insulin-induced decreased sensitivity to antitumor drugs can be ascribed to P-glycoprotein, the reversal of P-glycoprotein-mediated resistance is likely to work in the treatment of those obese patients who are not sensitive to conventional anti-cancer regimens." (PMID 26084465, 2015).
cancer (continued). "However, no compelling evidence that exogenous insulin or insulin analogues may elevate cancer risks has so far been presented." (PMID 25069390, 2014). "Thus one potential explanation for the lack of effect of XMetS on ligand induced proliferation of cancer cells may be related to the relatively limited effect of XMetS on insulin-dependent Erk activation." (PMID 24533136, 2014). "Importantly, XMetS does not potentiate insulin-stimulated proliferation of cancer cells." (PMID 24533136, 2014). "Therefore, some organs may be especially sensitive to exogenous insulin for cancer development, while others are not." (PMID 24991802, 2014). "Taken together, our results demonstrated that insulin and IGF-I signaling could in fact promote an invasive phenotype by changing the bisecting GlcNAc N-glycosylation profile of E-cadherin and consequently the expression pattern of epithelial/mesenchymal markers of cancer cells." (PMID 24282611, 2013). "Therefore, we do not know whether, in insulin-treated patients, glargine reaches plasma or tissue concentrations capable of affecting cancer cell growth." (PMID 23209929, 2012). "Thus, testing our hypothesis has provided evidence of a novel mechanism by which CAP modulates INS activity by means of allosteric enhancement of estrogen binding to its receptor, which has implications for understanding observed CAP effects in both metabolism and cancers." (PMID 40003617, 2025). "Our findings indicate that regular exercise significantly improved insulin levels and HOMA index in cancer patients, with a non-significant reduction in glucose." (PMID 40895542, 2025). "Molecularly, insulin’s effect on muscle protein synthesis is reduced in lung cancer patients with CAC compared to healthy controls, although no nonCAC cancer control patients were included." (PMID 41367198, 2025). "We found that the addition of insulin to ARG treatment at both low and high doses did not prevent the effects that arginine depletion has on cancer cells in vitro." (PMID 38374190, 2024). "In support of this latter option is the observation that caloric restriction in rodents decreases activity of the insulin/IGF-I signaling cascade and postpones or attenuates cancer, immunosenescence, and inflammation without irreversible side effects." (PMID 36901984, 2023). "Interestingly, while exploring the specific mechanism of metformin in decreasing blood glucose level and even cancer inhibition, some researchers found that MAPK signaling pathway could be inhibited by metformin and pancreatic aquaporin 7 (AQP7) was then reactivated to allow insulin secretion." (PMID 36973739, 2023). "As IGF-II expression is commonly upregulated in cancer and its signalling promotes cancer cell survival, an antagonist that blocks IGF-II action without perturbing insulin signalling would be invaluable." (PMID 35304516, 2022). "To do so, we exposed a panel of different cancer and noncancer cell lines (U2OS, MCF7, and RPE cells) to insulin, which is broadly used as stimulator of mTORC1 signaling, particularly in cells that have been previously starved from nutrients." (PMID 34033645, 2021). "Furthermore, expression of a constitutively active form of AKT1 by adenoviral vector prevents heart damage and protects mice from DOXO-induced cardiotoxicity, suggesting that the lack of insulin-mediated AKT1 activation during cancer progression could aggravate the cardiotoxicity induced by DOXO." (PMID 33547494, 2021). "However, it is not clear whether insulin and IGF-1 may promote cancer directly by promoting growth and preventing apoptosis, or by accelerating the aging process, which is a key risk factor for many cancers." (PMID 34572814, 2021). "A portion of the patients was randomly selected (17 cancer patients; 33 non-cancer patients) for a 75-g oral glucose tolerance test (OGTT), among whom multipoint (0, 0.5, 1, 2 and 3 h) serum insulin and CA125 tests were additionally performed." (PMID 29716620, 2018).